CDK4 (cyclin dependent kinase 4)
Diseases named in the same sentence as CDK4 in open-access papers (continued):
Sharing a sentence is not in itself a finding about the gene and the disease.
breast cancer (continued). "In ER+ breast cancer cells, estrogen receptor overexpression stimulates cell cycle progression through cyclin-dependent kinase 4 and 6 (CDK4/6) activation which drives cancer cell proliferation." (PMID 40341770, 2025). "Using preclinical HR+ human breast cancer models with acquired resistance to CDK4/6i, we demonstrate that maintaining CDK4/6i therapy, either alone or combined with CDK2 inhibitors (CDK2i), slows the growth of resistant tumors by prolonging G1 progression." (PMID 41459763, 2025). "Cell cycle re-entry of senescent breast cancer cells after CDK4/6 inhibition (CDK4/6i) constitutes a major source of disease recurrence." (PMID 39930269, 2025). "An increase in interleukin 17 (IL17) producing gamma/delta T cells occurred in mouse HR+HER2− mammary tumors following CDK4/6 inhibition." (PMID 40244377, 2025). "Apart from ER, no other reliable biomarkers are currently utilized for selecting combination therapy involving CDK4/6 inhibitors and endocrine therapy in breast cancer." (PMID 40740245, 2025). "The feasibility and acceptance of the DHHC among patients with breast cancer undergoing cyclin-dependent kinase 4/6 inhibitor therapy were evaluated in a prospective, single-arm, monocentric study." (PMID 40315425, 2025). "Further research and prospective validation in dedicated studies are essential to comprehensively assess the impact of PIK3CA status and different CDK4/6 inhibitors on clinical outcomes in HR+/HER2- advanced breast cancer." (PMID 40740245, 2025). "The phase III post-MONARCH trial was conducted on an ER+/HER2− advanced or relapsed breast cancer population progressing on ET plus CDK4/6i as a first-line treatment." (PMID 40244377, 2025). "Pharmacological inhibitors of cyclin-dependent kinases (CDK) 4 and 6 (CDK4/6i) inhibit breast cancer growth by inducing a senescent-like state." (PMID 39930269, 2025). "A retrospective cohort study of 105 Taiwanese breast cancer patients treated with palbociclib, a targeted CDK4/6 inhibitor, examined the prevalence of neutropenia associated with four SNPs: ABCB1_rs1045642, ABCB1_rs1128503, ERCC1_rs3212986, and ERCC1_rs11615." (PMID 40227705, 2025). "Guidelines for the first-line treatment of Hormone Receptor-positive, HER2-negative advanced or recurrent breast cancer have shifted to combination therapies of a CDK4/6 inhibitor and endocrine therapy." (PMID 40075731, 2025). "Despite these advancements, most patients with hormone receptor–positive/ERBB2–negative metastatic breast cancer experience disease progression during first-line ET plus CDK4/6i treatment due to the development of acquired tumor resistance." (PMID 39982725, 2025). "Recent work uncovers lysosomal alterations as a targetable co-vulnerability of CDK4/6 inhibitor-induced senescence in breast cancer cells." (PMID 39994486, 2025). "To further investigate the pivotal role of CDK4 expression in breast cancer (BRCA), we conducted an in-depth analysis by screening three gene expression datasets—GSE38959, GSE45827, and GSE65194—obtained from the Gene Expression Omnibus (GEO) database." (PMID 40864776, 2025). "This alternative approach led to the identification of GATAD1 as a synthetic lethal target with CDK4/6 inhibition in breast cancer through the induction of cell cycle arrest." (PMID 40650785, 2025). "As a result, the current guidelines recommend CDK4/6is combined with ET as the standard first-line therapy for HR+/HER2− advanced or relapsed breast cancer." (PMID 40244377, 2025). "PERCEPTION proved effective in predicting responses to CDK4/6 inhibitors in breast cancer and tyrosine kinase inhibitors in lung cancer." (PMID 39941808, 2025). "In the recent TROPION-PanTumor01 phase I trial, datopotamab deruxtecan, an ADC similar to trastuzumab deruxtecan, showed promising activity and low toxicity in heavily pretreated ER+/HER2− breast cancer subjects, most of them treated with a CDK4/6i." (PMID 40244377, 2025).
breast cancer (continued). "The identity of the cognate CAK that phosphorylates CDK4 at T172 in ER+ breast cancer cells remains elusive." (PMID 41226361, 2025). "The data collectively showed that NSRP1 negatively regulated CDK4/6i resistance in breast cancer cells." (PMID 39667501, 2025). "For example, the CDK4 inhibitor Palbociclib treats breast cancer by inducing cell cycle arrest and senescence." (PMID 41319797, 2025). "In HER2-positive breast cancer, the concomitant administration of the HER2 inhibitor lapatinib and the CDK4/6 inhibitor abemaciclib has demonstrated efficacy in suppressing breast cancer cells that exhibit resistance to lapatinib." (PMID 40563591, 2025). "The development of cyclin-dependent kinase 4/6 (CDK4/6) inhibitors such as ribociclib, abemaciclib, and palbociclib, revolutionized the management of metastatic ERα+ breast cancer, doubling progression-free survival on first-line therapy." (PMID 40206590, 2025). "Overall, 27 patients (38.0%) receiving capivasertib–fulvestrant and 23 patients (36.5%) receiving placebo–fulvestrant had been previously treated with CDK4/6 inhibitor for advanced breast cancer." (PMID 40346047, 2025). "The data also identified AS events and the IFN pathway regulated by NSRP1 in breast cancer cells, providing novel insights into understanding the development of CDK4/6i resistance and optimizing treatment strategies for patients." (PMID 39667501, 2025). "Mechanistically, this CAF subset was shown to compromise the efficacy of CDK4/6 inhibitors in both breast cancer cell lines and xenograft models through the exosomal delivery of miR-20, which in turn suppressed Rb expression." (PMID 41388212, 2025). "In contrast, our study’s strength lies in its homogenous patient population, specifically focusing on individuals with breast cancer receiving CDK4/6 inhibitor therapy in combination with endocrine therapy." (PMID 40005476, 2025). "As the first CDK4/6i approved by the FDA for use in combination with endocrine therapy in patients with HR+/HER2- advanced breast cancer (ABC), palbociclib demonstrated impressive therapeutic efficacy in the PALOMA-1/TRIO-18 phase II clinical trial." (PMID 40134916, 2025). "For advanced HR-positive, HER2-negative breast cancer, first-line treatment typically consists of ET combined with a cyclin-dependent kinase 4/6 inhibitor (CDK4/6i)." (PMID 41463269, 2025). "We previously reported that patients with breast cancer treated with CDK4/6 inhibitors who had a favorable immune environment, as indicated by peripheral blood biomarkers at the start of treatment, had better outcomes." (PMID 40295416, 2025). "The CDK2 selective catalytic inhibitor INX-315 induced a potent growth arrest in the CDK2-addicted models, which closely mirrors the effect of palbociclib in CDK4-addicted ER+ breast cancer models." (PMID 39924553, 2025). "While intrinsic resistance to CDK4/6i is less frequent (approximately 20% of breast cancers), acquired resistance is a common clinical challenge." (PMID 40764324, 2025). "Preclinical findings indicate potential synergistic effects between cisplatin and CDK4/6 inhibitors in several cancers, such as esophageal squamous cell carcinoma, ovarian cancer, bladder cancer, and breast cancer." (PMID 40456804, 2025). "In research, the lncRNA TROJAN led to CDK2 upregulation by linking to NKRF and blocking its inhibition on RELA/p65, so contributing to the decreased response of ER+ breast cancer cells to CDK4/6is." (PMID 40244377, 2025). "Vitiligo-like skin lesions have been reported as rare but documented adverse effects in breast cancer patients treated with CDK4/6 inhibitors such as ribociclib and palbociclib." (PMID 40422590, 2025). "The three-year cumulative incidences of ATE and VTE were 2.6% (95% CI: 1.9–3.5) and 6.9% (95% CI: 5.7–8.3) after initiation of CDK4/6-inhibitors, and 2.3% (95% CI: 1.6–3.2) and 7.1% (95% CI: 5.9–8.5) in the subgroup of patients with breast cancer." (PMID 40896464, 2025).
breast cancer (continued). "Clinical studies have demonstrated that the CHEK1 inhibitor AZD7762 synergizes with CDK4/6 inhibitors in HR+ breast cancer models, highlighting the potential of CHEK1 as a cross-subtype therapeutic target." (PMID 40344565, 2025). "The clinical application of CDK4/6i has expanded significantly from their initial use in advanced/metastatic breast cancers to early-stage disease settings." (PMID 40377782, 2025). "Abemaciclib, a CDK4/6 inhibitor, has emerged as a pivotal therapy in hormone receptor–positive, HER2-negative breast cancer, including in the adjuvant setting for high-risk early disease." (PMID 41496427, 2025). "PI3K/AKT/mTOR pathway-targeted medicines are presently employed as second-line therapy for HR+ MBC, primarily in patients with breast cancer who have had prior CDK4/6is progress." (PMID 40134916, 2025). "This study is noteworthy as it is the first clinical trial to utilize CDK4/6is in treating premenopausal breast cancer patients, offering a new treatment option for those with advanced disease." (PMID 40134916, 2025). "The cyclin D:CDK4/6 complex is a factor that promotes breast cancer progression, and CDK4/6 inhibitors have recently been administered to patients with unresectable or recurrent Luminal breast cancer." (PMID 39604563, 2025). "CDK4/6 inhibitors plus endocrine therapy is a pivotal treatment option for HR(+)/HER2(−) breast cancer based on their efficacy and safety." (PMID 40922517, 2025). "Here we examine the molecular mechanisms regulating the cell cycle, current clinical applications of CDK4/6 inhibitors in breast cancer, and key mechanisms contributing to drug resistance." (PMID 39930131, 2025). "CDK4/6 inhibitors are drugs used to treat certain types of HR+/HER2- breast cancer by blocking the cyclin-dependent kinases 4 and 6 (CDK4/6) enzymes, which are crucial for cell division." (PMID 41301715, 2025). "A better understanding of the real-world safety profile of CDK4/6 inhibitors in patients with HR+ breast cancer will lead to better compliance and fewer interruptions and reflect on the desirable progression-free survival and overall survival." (PMID 41458615, 2025). "The treatment landscape for advanced HR+)/HER2− breast cancer has been transformed by the introduction of CDK4/6 inhibitors in the first-line setting." (PMID 41226406, 2025). "Cyclin-dependent kinase 4/6 inhibitors and endocrine maintenance therapy are effective treatments for breast cancer brain metastases." (PMID 40161091, 2025). "The current standard of care for advanced HR+/HER2− breast cancer is endocrine therapy combined with CDK4/6 inhibitors." (PMID 41562776, 2025). "In patients with locally advanced or metastatic ER‐positive/HER2‐negative breast cancer, ET with either aromatase inhibitors (AI) or fulvestrant plus a cyclin‐dependent kinase 4/6 (CDK4/6) inhibitor is recommended as first‐line standard of care (SOC)." (PMID 38867388, 2025). "Over 80% of metastatic HR+/HER2− breast cancer patients now receive CDK4/6 inhibitors as first-line therapy." (PMID 40421216, 2025). "Clinically, SY-5609 is undergoing evaluation in early-phase trials (e.g., NCT04247126) for treatment-refractory solid tumors, including advanced HR + breast cancer following CDK4/6i failure, pancreatic ductal adenocarcinoma, and biliary tract malignancies." (PMID 40949156, 2025). "A study included 79 patients with advanced breast cancer treated with CDK4/6 inhibitors, documenting a total of 165 cutaneous adverse events." (PMID 40422590, 2025). "This work aims to examine the impacts of radiotherapy in combination with the CDK4/6 inhibitor abemaciclib versus abemaciclib administered alone on breast cancer cell lines." (PMID 40035822, 2025). "Cyclin D is also a target of TAZ in breast cancer stem cells and hippo/YAP/TAZ is a pathway promoting CDK4/6 resistance in breast cancer too, implying a global role of hippo/YAP/TAZ in cell cycle transition regulation." (PMID 40699853, 2025).
breast cancer (continued). "A phase I/II trial enrolled HER−relapsed breast cancer subjects who had already received CDK4/6is (87%), fulvestrant (71%), or chemotherapy (54%), with 58% of them carrying ESR1 mutations." (PMID 40244377, 2025). "Overall, the evidence for CDK4/6i continuation beyond progression is encouraging but mixed, underscoring the need for mechanistic studies of CDK4/6i-resistant proliferation to guide post-progression treatment strategies for HR+/HER2− breast cancer." (PMID 39605351, 2025). "In HER2-positive breast cancer, this technology has investigated combinatorial immunotherapy strategies for CDK4/6 inhibitor resistance by elucidating rapidly evolving resistance mechanisms." (PMID 40843360, 2025). "Ongoing clinical trials are currently assessing novel combinations such as PF-07104091 (CDK2-selective inhibitor) with PF-07220060 (CDK4-selective inhibitor) plus ET in advanced HR+/HER2− breast cancer (NCT05262400)." (PMID 40243688, 2025). "We next sought to test the therapeutic potential of ERK/CDK4/6 drug inhibition on mammary tumour growth by E/M cells." (PMID 40764669, 2025). "The clinical efficacy of CDK4/6 inhibitors has transformed the landscape of metastatic breast cancer treatment, with improved outcomes even in the presence of certain mutations that contribute to endocrine resistance." (PMID 40244189, 2025). "The FDA has approved three different CDK4/6 inhibitors to treat ER+/HER-2 breast cancer, but these treatments have inefficient results in TNBC." (PMID 41463161, 2025). "These insights are highly relevant to contemporary treatment strategies, particularly in light of emerging evidence supporting the addition of CDK4/6 inhibitors to address hormone resistance in ER+/HER2+ breast cancer." (PMID 40683772, 2025). "Currently, three CDK4/6 inhibitors, palbociclib, ribociclib, and abemaciclib, have been approved as drugs for treating breast cancer by the U.S. Food and Drug Administration." (PMID 39565117, 2025). "Previous studies have shown that HR+/HER2− breast cancer patients with CDKN2A overexpression achieve a better response to CDK4/6i, suggesting a beneficial role for enhancing drug sensitivity." (PMID 41357671, 2025). "Given the critical role of CDK4/6 in HR + breast cancer and their increasing relevance in aggressive cancers such as triple-negative breast cancer (TNBC), we evaluated LA-CB1’s therapeutic potential in multiple cancer models." (PMID 40038413, 2025). "There is a need to better understand mechanisms of intrinsic resistance and early adaptive responses to ET/CDK4/6i therapy to extend breast cancer control time in the first-line setting." (PMID 39865083, 2025). "This study provides the first comprehensive economic evaluation of first-line versus second-line use of CDK4/6 inhibitors combined with endocrine therapy for advanced HR+/HER2- breast cancer in China." (PMID 41383485, 2025). "Recent studies have highlighted the critical role of CDK4/6 in the regulation of cell cycle progression, particularly in breast cancer." (PMID 40864776, 2025). "In breast cancer cells a combinatorial drug screening found that CDK4/6 inhibition exhibits the most significant synergism with PI3K inhibitors." (PMID 40260297, 2025). "The NATALEE and monarchE trials have demonstrated the efficacy of CDK4/6 inhibitors in early breast cancer." (PMID 40149336, 2025). "Among these targets, the combination of CDK4/6i with ER-targeted agents has shown a remarkable improvement in prolonging the survival of ER + breast cancer patients compared with ER-targeted agents alone." (PMID 39667501, 2025). "In this study, we discovered a role of ERBB pathway activation in driving GF signal-mediated proliferation of endocrine and CDK4/6i-resistant ER+ breast cancer cells." (PMID 40341770, 2025). "Despite the initial success of CDK4/6 inhibitors in treating HR+/HER2− breast cancer, most patients eventually develop drug resistance, limiting the long-term efficacy of this treatment." (PMID 39930131, 2025).
breast cancer (continued). "PI3K inhibitors can block the early adaptation of HR+ breast cancer to CDK4/6i and prevent the acquisition of CDK4/6i resistance." (PMID 39910045, 2025). "We then sought to deploy PROFET to investigate heterogeneity in treatment response to palbociclib, a CDK4/6 inhibitor used in HR+ breast cancer that is known to induce variable treatment responses." (PMID 40631077, 2025). "This sequential therapeutic strategy offers a promising approach to eliminate CDK4/6i-induced senescent(-like) cells, potentially reducing tumor recurrence and enhancing the overall efficacy of breast cancer therapy." (PMID 39930269, 2025). "In a recent exploratory, prospective, cross-sectional study of 14 breast cancer patients treated with CDK4/6 inhibitors, specific fecal microbiota profiles were also associated with response to therapy." (PMID 41236788, 2025). "As the use of CDK4/6 inhibitors in the treatment of HR + /HER2- breast cancer patients becomes more widespread, rare adverse events and long-term safety issues have not yet been systematically reported." (PMID 41259313, 2025). "Here, we performed unbiased genome-wide CRISPR/Cas9 knockout screens using endocrine sensitive ER+ breast cancer cells to identify novel drivers of resistance to combination endocrine therapy (tamoxifen) and CDK4/6 inhibitor (palbociclib) treatment." (PMID 40826108, 2025). "For HR+/HER2- advanced breast cancer, CDK4/6 inhibitors are increasingly utilized with supporting evidence from trials like monarchE." (PMID 40263332, 2025). "Other drugs, such as epidermal growth factor receptor (EGFR) tyrosine kinase inhibitors for lung cancer and cyclin-dependent kinase 4 and 6 (CDK4/6) inhibitors for breast cancer demonstrate high efficacy, but they are also associated with DIILD." (PMID 40452849, 2025). "This review focuses on the evolving therapeutic landscape for advanced HR+/HER2-negative breast cancer, with specific attention to treatments following disease progression on standard first-line therapy with CDK4/6 inhibitors." (PMID 41226406, 2025). "The integration of CDK4/6 inhibitors represents a significant advancement in the treatment of HR+ HER2− breast cancer." (PMID 40277749, 2025). "In these breast cancers, new generations of ER inhibitors have already entered clinical trials in combinations with CDK4/6 inhibitors to circumvent resistance related to altered ER signaling." (PMID 40699853, 2025). "In advanced ER + breast cancer, the use of chemotherapy and CDK4/6 inhibitors is also beneficial; however, resistance to these therapies quickly renders them ineffective in many cases." (PMID 40650785, 2025). "Our data suggest that the activation of FGF signaling confers resistance to CDK4/6 inhibitors and ET and that tasurgratinib shows antitumor activity in combination with ET in ET-resistant ER+ breast cancer." (PMID 40227585, 2025). "While CDK4/6 inhibitors such as palbociclib have demonstrated significant clinical efficacy in hormone receptor-positive (HR+) breast cancer, their role in TNBC remains under active investigation." (PMID 40864776, 2025). "Based on the clinical samples and multiple established CDK4/6i resistant breast cancer cell lines, a previous study reported a close connection between activation of the IFN pathway and CDK4/6i resistance." (PMID 39667501, 2025). "Regarding the activation of alternative pathways, genetic alterations in AKT1, AURKA, and KRAS have been identified in HR+/HER2− breast cancer that is resistant to CDK4/6is." (PMID 40244377, 2025). "While selective CDK4/6 inhibitors like Palbociclib, Ribociclib, and Abemaciclib have shown clinical benefit in hormone receptor-positive (HR+) breast cancer, their efficacy is often limited by resistance mechanisms and dose-limiting toxicities." (PMID 40038413, 2025).